S100A12 (S100 calcium binding protein A12)
Diseases named in the same sentence as S100A12 in open-access papers (continued):
Sharing a sentence is not in itself a finding about the gene and the disease.
Sepsis (continued). "In addition, S100A12 expression was not significantly different between the sepsis follow-up group and the uncomplicated infection group (p = 0.26)." (PMID 34108608, 2021). "This indicates that persistent expression of S100A12 by immune cells might not be a bad thing since S100A12 could prevent IL-10 overproduction known to be involved in the immunosuppression in the late stage of sepsis." (PMID 35723375, 2022). "This suggests that in the case of our Gram-negative, bacterial induced sepsis patients, there is an activation of the NLRP3 inflammasome pathway involved in the increased expression of S100A12 in the pathogenesis of sepsis-induced ARDS." (PMID 36979757, 2023).
psoriasis (33 papers, 2012 to 2026). An autoimmune condition characterized by red, well-delineated plaques with silvery scales that are usually on the extensor surfaces and scalp. "S100A12 has been implicated in various inflammatory conditions, including psoriasis and cardiovascular diseases." (PMID 39014096, 2024). "Among S100 proteins, the serum S100A12 level revealed the closest association with psoriasis disease activity-PASI." (PMID 33681365, 2021). "High levels of S100A12 protein have been associated with several inflammatory diseases such as rheumatoid arthritis, inflammatory bowel disease, and psoriasis." (PMID 27355424, 2016). "Further analysis found that RORC and S100A12 were associated with psoriasis severity." (PMID 33681365, 2021). "It was also suggested that S100A12, also called calgranulin-c, might be the most promising bioindicator of psoriasis with the closest association with the disease activity evaluated by PASI." (PMID 32377165, 2020). "Through ST analysis, we identified nonrandom expression patterns of specific gene features associated with hypoxia, showing differential expression gradients between differentiated KCs and RHCG/S100A12 in psoriasis samples." (PMID 40351602, 2025). "S100A7A and S100A12, part of the S100 protein family, are primarily involved in inflammatory processes and are upregulated in psoriasis, thereby exacerbating inflammation." (PMID 40959079, 2025). "First, we observed a strong correlation between RHCG and S100A12, a calcium-binding protein known to be upregulated in inflammatory conditions, including psoriasis." (PMID 40351602, 2025). "The serum concentrations of S100A12 in both CD and psoriasis patients markedly exceeded optimal levels and exhibited a association with the severity of the disease." (PMID 40540498, 2025). "Like other calcium-binding proteins, S100A12 is upregulated in inflammatory conditions and is believed to play a significant role in the immunopathology of psoriasis." (PMID 40351602, 2025). "In psoriasis, key proinflammatory genes, including S100A12, had more robust expression when obtained via tape stripping as compared with full-thickness biopsies." (PMID 40080076, 2025). "There are many evidences indicating the presence of S100A12 in several inflammatory diseases, like rheumatoid arthritis and psoriasis, as well as in infections." (PMID 38301897, 2024). "Consistently, TNF-α inhibitor treatment accelerates hypomethylation in CpG islands in S100A12, suggesting epigenetic regulation of S100A12 proteins in psoriasis." (PMID 37891988, 2023). "In the psoriatic epidermis, S100A12 is expressed in the suprabasal epidermal layers, and its expression levels correlate positively with psoriasis severity." (PMID 37346040, 2023). "In support of the preceding finding, new research has revealed significantly elevated expression of alarmins, such as IL-33, HMGB1, S100A7, and S100A12, in serum, implying a role for these alarmins in the immunopathology of psoriasis conditions." (PMID 35892571, 2022). "The pathways associated with the ubiquitination-proteasome system were significantly regulated by RORC and S100A12 alteration in psoriasis." (PMID 33681365, 2021). "S100A7 (psoriasin), S100A8 (calgranulin A), S100A9 (calgranulin B), and S100A12 (calgranulin C) are markedly increased in psoriasis lesions." (PMID 29619128, 2018). "S100A12 (calgranulin C) have been also shown to be overexpressed in psoriatic plaques; however its exact role in psoriasis need further investigation." (PMID 24901012, 2014). "Subsequently, WGCNA showed the hub genes (e.g., S100A12, CYCS, NOD2, STAT1, HSPA4, AIM2, MAPK7), which were significantly associated with clinical phenotype, PANoptosis signature, and identified immune response in psoriasis." (PMID 38125299, 2024).
psoriasis (continued). "Additionally, serum S100A7 (psoriasin) and S100A12 (calgranulin-c) were found to be elevated in psoriasis patients, with the latter being regarded as the most promising S100 protein biomarker thus far in terms of correlating with severity of psoriasis." (PMID 37546687, 2023). "A genome-wide study identified hypermethylation in CpG islands in psoriatic skin and showed a negative association with S100A12 expression, which is highly elevated in psoriasis." (PMID 37891988, 2023). "The inflamed synovium expresses S100A12 in the tissue, which is impaired by psoriasis treatment." (PMID 37891988, 2023). "Blood levels of S100A12 are elevated in patients with diabetes, coronary artery disease, and psoriasis, and this protein is also used as a biomarker to detect other inflammatory diseases such as systemic juvenile idiopathic arthritis or acute infectious exacerbations common in cystic fibrosis." (PMID 36235175, 2022). "Interestingly, S100A8, S100A9 and S100A12 protein levels are used as sensitive biomarkers for monitoring disease activity in juvenile idiopathic arthritis, inflammatory bowel disease and psoriasis." (PMID 35055093, 2022). "S100A12 was considered the most promising active marker for psoriasis in the Wilsmann-Theis study." (PMID 35693833, 2022). "Small subsets of S100 (for example, S100A7, S100A8, S100A9, and S100A12) have been shown to be upregulated in psoriasis skin lesions, whereas transcriptomics and ELISA-based approaches indicate that S100A12 is strongly correlated with a functional disease condition." (PMID 35892571, 2022). "This suggests that the expression of RORC and S100A12 might be regulated by ubiquitination, which is related to the modulation of psoriasis severity." (PMID 33681365, 2021). "The alarmins HMGB1, IL-33, S100A7, and S100A12 were significantly elevated in the serum of patients, which states the hypothesis that they play specific roles in the immunopathology of psoriasis." (PMID 32377165, 2020). "HMGB1, IL-33, S100A7, and S100A12 were chosen as the most promising alarmins according to the literature, because they were reported to be elevated in various autoimmune diseases, yet their role in pathophysiology of psoriasis is still unclear." (PMID 32377165, 2020). "Studies have shown that S100A12, also classified as an epithelial cytokine, is expressed at very low levels in normal epidermis, but it is highly overexpressed in lesions of psoriasis, UVB-irradiated skin, and tape-stripping of the skin induce fast and long-lasting AMP expression." (PMID 30728947, 2019). "Among them, 10 genes including the inhibitor of DNA binding 4 (ID4), heparin binding protein 17 (HBP-17), keratin 16 (KRT16), S100A2, S100A9, S100A12, guanine nucleotide binding protein 15 (GNA15), MTX, PRKMK3, and SCYA2 were all found to be localized in the psoriasis susceptibility loci." (PMID 26362816, 2015). "Normal human keratinocytes were found to constitutively bear the IL-17 receptor (IL-17R) and they are able to produce several IL-17-induced inflammatory and immune-related mediators implicated in psoriasis pathogenesis (e.g. IL-8, CCL20, S100A12, CXCL1, and CXCL2)." (PMID 24587313, 2014). "To further investigate the role of SLPI, S100A9, IL1B, CYBB, CXCL8, S100A12, and CXCL1 genes in the immune microenvironment of psoriasis, we examined inflammatory cell infiltration." (PMID 39014096, 2024). "To identify potential therapeutic options for psoriasis and AMI, we screened drugs targeting CXCL8, IL1B, S100A9, and S100A12 using the DsigDB database." (PMID 39014096, 2024). "The expression levels of several S100 proteins, such as S100A2, S100A7, S100A8/S100A9, S100A12, and S100A15, are significantly up-regulated in psoriasis-involved skin." (PMID 37346040, 2023). "The binding of S100A12 to the RAGE V domain increases cellular inflammatory response to oxidative stress and participates in the pathogenesis of psoriasis." (PMID 37346040, 2023).
psoriasis (continued). "However, the detailed mechanisms of action of S100A12 in psoriasis and AD remain unclear." (PMID 37891988, 2023). "S100A7 (psoriasin), S100A8 (calgranulin A), S100A9 (calgranulin B), S100A12 (calgranulin C), and S100A15 are highly expressed in psoriasis." (PMID 33050592, 2020). "There are inverse correlations between expression of nearby genes and methylation at these sites, including KYNU, OAS2, S100A12, and SERPINB3, whose strong transcriptional upregulation acts as a key indicator of psoriasis." (PMID 26362816, 2015). "IL-17 also induced a number of anti-microbial peptides, including S100A12, S100A7A, SERPINB4, SERBINB3, which are highly expressed in psoriasis, as has been described previously." (PMID 24587313, 2014). "Additionally, we explored the skin lesions of psoriasis patients and found significantly higher expression of CXCL8, IL-1B, S100A9, and S100A12 in the affected skin areas compared to unaffected regions." (PMID 39014096, 2024). "Members of the S100 family of proteins intensively studied in the course of psoriasis include S100A4 (Figure A1), S100A7 (Figure A2), S100A8 (Figure A3), S100A9 (Figure A4), S100A12 (Figure A5), S100B (Figure A6) and S100A15, indicating their involvement in the pathogenesis of the disease." (PMID 36235175, 2022). "Twenty-one S100 proteins are known, of which S100A7 (psoriasin), S100A8 (calgranulin A), S100A9 (calgranulin B), S100A12 (calgranulin C), and S100A15 have antimicrobial effects and their expression levels are increased in the lesional skin and serum of psoriasis patients." (PMID 32947991, 2020). "For example, S100A4 is involved in autoimmune pancreatitis, S100A11, S100A8 and S100A9 in rheumatoid arthritis, S100A1 in hypoxia-induced inflammatory response in cardiomyocytes, S100A12 in Crohn’s disease, S100A7 and S100A7A in psoriasis, S100A8, S100A9 and S100A12 in systemic lupus erythematosus." (PMID 30018736, 2018). "Approximately 60% of the top 20 upregulated genes, such as S100A12, SPRR2C, and CXCL1, have additive or synergistic responses to IL-17 and TNF, suggesting that these cytokines will be important for the creation of a molecular profile for psoriasis." (PMID 26362816, 2015). "Most well known psoriasis related genes activated in non-lesional skin are IL6, IL22, IL36A, IL36G, IL19, IL20, S100A7 and S100A12." (PMID 25897967, 2015).
rheumatoid arthritis (28 papers, 2006 to 2025). A chronic, systemic autoimmune disorder characterized by inflammation in the synovial membranes and articular surfaces. "Previous studies suggested that an increase of S100A12 is associated with several inflammatory diseases, such as inflammatory bowel disease, rheumatoid arthritis, juvenile idiopathic arthritis, cystic fibrosis, and periodontitis." (PMID 34745092, 2021). "Increased S100A12 is associated with rheumatoid arthritis and inflammatory bowel disease, both of which are characterized by aberrant inflammatory states." (PMID 34108966, 2021). "S100A8, S100A9, and S100A12 encode proteins that are well-known markers of acute inflammation and previously implicated in several other inflammatory and autoimmune diseases including systemic lupus erythematosus, rheumatoid arthritis, and atherosclerosis." (PMID 32556497, 2020). "Clinical data strongly support the utility of S100A12 as a precise and sensitive indicator to detect inflammation, with noted increases in its serum levels in those with rheumatoid arthritis." (PMID 39813538, 2025). "In 2004, Foell and his colleagues found the over-expression of S100 proteins, particularly S100A8, S100A9, and S100A12, at the site of inflammation in Rheumatoid arthritis, chronic inflammatory lung, and bowel disease." (PMID 38956704, 2024). "Mounting evidence clarified that S100A12 is elevated and involved in several inflammatory diseases, such as inflammatory bowel disease, rheumatoid arthritis, juvenile idiopathic arthritis, cystic fibrosis, and periodontitis." (PMID 34745092, 2021). "S100A12 expression is higher in several chronic inflammatory diseases, such as rheumatoid arthritis and inflammatory bowel disease." (PMID 32082330, 2020). "For example, S100A12 has been described as biomarker for rheumatoid arthritis, TB as well as inflammatory bowel disease." (PMID 32849645, 2020). "The S100A12 expression is high in inflammatory diseases such as rheumatoid arthritis, Crohn’s disease, Kawasaki disease, and atherosclerosis." (PMID 23324110, 2013). "MRPs haveproinflammatory effects in the extracellular milieu.S100A12 is detected in the synovial fluid and plasma of patientswith gout, rheumatoid arthritis, and psoriatic arthritis,suggesting that S100A12 may be involved in the inflammation inthese diseases." (PMID 16864903, 2006). "S100A12 (also known as calgranulin C) belongs to the S100/calgranulin-protein family and represents a useful inflammatory marker in human patients with inflammatory diseases, such as systemic lupus erythematosus, rheumatoid arthritis, respiratory disease and IBD." (PMID 26370713, 2015). "The calcium-binding protein S100A12 correlates with measures of disease activity in patients with rheumatoid arthritis (RA)." (PMID 25282581, 2014). "High concentrations of three of its putative proinflammatory ligands, S100A8/A9 complex (calprotectin), S100A8, and S100A12, are found in rheumatoid arthritis (RA) serum and synovial fluid." (PMID 19284577, 2009). "Previous studies demonstrated that KYNA reduces TNF-α, S100A12, S100A8/9, and α-defensin production while increasing tumor necrosis factor-stimulated gene-6 protein (TSG-6) levels in rheumatoid arthritis." (PMID 41465233, 2025). "Studies have demonstrated that S100A12 and S100A8 are potential biomarker for disease severity and prognosis in some diseases, such as Idiopathic Pulmonary Fibrosis, Rheumatoid Arthritis, Blau syndrome, Chronic Spontaneous Urticaria, active lupus nephritis, and dilated cardiomyopathy." (PMID 40415930, 2025). "It is certain that the content of S100A8, S100A9, and S100A12 proteins in serum or fecal are closely related to diseases and can be used as biomarkers for their detection and diagnosis, including rheumatoid arthritis (RA), inflammatory bowel disease (IBD), cancer, etc.." (PMID 38256103, 2024).
rheumatoid arthritis (continued). "Furthermore, SZR72 inhibited the production of the inflammatory mediators TNF-α, calprotectin, S100A12, and HNP1-3 in blood cultures of rheumatoid arthritis patients." (PMID 35163002, 2022). "S100A8 and S100A12 are up-regulated in chronic inflammatory conditions, including asthma, rheumatoid, and inflammatory arthritis, perhaps reflecting a more general pathophysiological signal, consistent with increased CAD in disorders such as rheumatoid arthritis." (PMID 21443790, 2011).
atherosclerosis (27 papers, 2009 to 2025). A disease characterized by the build-up of fatty material and calcium deposition in the arterial wall resulting in partial or complete occlusion of the arterial lumen. "It has been shown that there is a significant correlation between S100A12 and the risk of atherosclerosis in patients with diabetes mellitus (DM) and end-stage renal disease." (PMID 40269701, 2025). "Elevated levels of the calcium-binding protein S100-A12 are associated with reduced cardiac output and increased risk of heart failure, also serving as an independent risk factor for atherosclerosis." (PMID 38827362, 2024). "Elevated S100A12 expression has been associated with various inflammatory conditions, including arthritis, inflammatory bowel disease, and atherosclerosis, making it a key indicator of inflammation." (PMID 39037979, 2024). "S100A12 is a member of the S100 multigene family, a calcium binding protein which is highly associated with chronic inflammatory disorders, including atherosclerosis and coronary artery disease (CAD)." (PMID 34977174, 2021). "Serum levels of S100A12 have been associated with atherosclerosis in many cohort studies, and the Rotterdam study was the first longitudinal study to suggest a causal role of S100A12 for coronary artery disease." (PMID 30467547, 2018). "It is reasonable to hypothesize that the inflammatory response mediated by S100A12 promotes the formation and progression of atherosclerosis in people with dyslipidemia, thereby increases the risk of PAD." (PMID 40269701, 2025). "Lastly, our review encountered robust literature on the association of S100A12 with atherosclerosis, a well-known systemic inflammatory disease that may affect abdominal arteries." (PMID 32184815, 2020). "These animals were created to probe whether S100A12 causes atherosclerosis, since many human cohort studies showed an association of S100A12 with atherosclerosis." (PMID 30467547, 2018). "Furthermore, S100A9 and S100A12 are implicated in vascular damage, whereas sRAGE is associated with vascular protection in atherosclerosis." (PMID 19284577, 2009). "The S100 proteins S100A8, S100A9, and S100A12 play a crucial role in inflammation and atherosclerosis, while S100A1 plays a role in post-ischemic angiogenesis." (PMID 35203642, 2022). "Therefore, S100A12 is used as a subclinical indicator of inflammation or microbial infection, and the increase in the blood concentration of S100A12 protein has been associated with Type 2 diabetes, atherosclerosis-related inflammation, and tumorigenic processes." (PMID 35778422, 2022). "S100A12 augmented the atherosclerosis-triggered osteogenesis and TNF-α increased the expression of RAGE." (PMID 34497344, 2021). "Importance: S100A12 is a calcium binding protein which is involved in inflammation and progression of atherosclerosis." (PMID 34977174, 2021). "A number of studies reported that S100A12 is markedly expressed in several inflammatory disorders such as atherosclerosis, inflammatory bowel disease, Kawasaki disease and coronary artery disease." (PMID 31993369, 2019). "High circulating levels of S100A12 are present in sera from patients with chronic inflammatory diseases including atherosclerosis, rheumatoid arthritis and Kawasaki disease." (PMID 23638054, 2013). "S100A12 is a potent monocyte chemoattractant and activates mast cells, which are important effector cells in RA and atherosclerosis." (PMID 19284577, 2009). "Moreover, there are insufficient studies on the direct effect of S100A12 on ischemia/ischemia-reperfusion injury, though S100A12 promotes atherosclerosis and vascular calcification." (PMID 38538601, 2024). "High levels of S100A12 may alter the cellular microenvironment and promote the formation of atherosclerosis by activating mast cells." (PMID 37217870, 2023). "Since inflammation links hypercholesterolemia to atherosclerosis, S100A12 may help to better define the burden of atherosclerosis in patients with high cholesterol levels." (PMID 37217870, 2023).